CXCL5 (C-X-C motif chemokine ligand 5)
Diseases named in the same sentence as CXCL5 in open-access papers (continued):
Sharing a sentence is not in itself a finding about the gene and the disease.
melanoma (continued). "Moreover, CXCL5-overexpressing melanoma cells recruited high amounts of neutrophils and exhibited significantly increased lymphangiogenesis in a mouse melanoma xenograft model." (PMID 36980564, 2023). "Furthermore, baseline serum CXCL5 and increased serum levels of CCL19 and CCL26 were significantly associated with the efficacy of nivolumab in advanced melanoma." (PMID 35409404, 2022). "Similarly, in lung adenocarcinoma, CXCL2 secretion by αSMA+ CAFs increases PD-L1 expression by tumor cells and αSMA+ CXCL5-secreting CAFs are positively correlated to PD-L1 expression by melanoma and colorectal carcinoma tumor cells." (PMID 36338519, 2022). "CXCL5 is a cytokine that also participates in melanoma drug resistance acquisition." (PMID 33430277, 2021). "Similarly, in melanoma, MDSCs recruited via CXCL5 have been shown to induce EMT by producing factors such as TGF-β, EGF, and HGF, and when depleted, the rate of metastasis in animal models is greatly reduced." (PMID 34830780, 2021). "In addition, increased intratumoral CXCL1 level in RET transgenic mice, in contrast to CXCL5, significantly correlated with the accumulation of melanoma infiltrating PMN-MDSC." (PMID 33578808, 2021). "CXCL5 expression is significantly increased in patients with advanced melanoma." (PMID 33042821, 2020). "CXCL5 facilitates melanoma cell-neutrophil interaction and lymph node metastasis." (PMID 32632106, 2020). "The present study suggested that CXCL5 may be a useful biomarker for the selection of those melanoma patients most likely to benefit from anti-melanoma immunotherapy using nivolumab and ipilimumab combined therapy." (PMID 31080803, 2019). "Furthermore, in a metastatic murine xenograft model, overexpression of CXCL5 in human melanoma cells elicited increased neutrophil recruitment and neutrophil dependent tumor cell migration into lymphatic vessels leading to lymph node metastasis." (PMID 30899263, 2019). "CXCL5 was upregulated in human stage T4 melanoma biopsies, which correlated with greater neutrophil infiltration and locoregional metastasis, when compared to stage T1 human melanomas." (PMID 30899263, 2019). "Taken together, CXCL5 may represent a predictive biomarker for evaluating the efficacy of nivolumab 3 months after its first administration for advanced melanoma." (PMID 31080803, 2019). "This study suggests that sCD163 and CXCL5 may serve as possible prognostic biomarkers for irAEs in patients with advanced melanoma treated with nivolumab." (PMID 29643991, 2018). "Notably, immunofluorescence staining revealed that CD163+ macrophages were distributed in POSTN-expressing areas, suggesting that POSTN in melanoma can stimulate CD163+ macrophages to produce CXCL5." (PMID 29643991, 2018). "To determine whether serum levels of sCD163 and CXCL5 may predict AEs in patients treated with nivolumab, we evaluated their levels in 46 patients with advanced melanoma treated with nivolumab." (PMID 29643991, 2018). "We previously reported that both CXCL5 and sCD163 might predict irAEs in 17 patients with advanced melanoma patients treated with nivolumab." (PMID 29643991, 2018). "Of note, CXCL1 and IL-8, the human ortholog of CXCL5, are expressed by human melanoma cells." (PMID 21980263, 2011). "In melanoma, CAF secreted CXCL5 and upregulated programmed cell death protein 1 (PD-L1) expression in cancer cells." (PMID 41392310, 2025). "Neutrophil recruitment is mainly mediated by chemokines with glutamate-leucine-arginine motifs (ELR+ chemokines), mainly melanoma growth-stimulating activity (CXCL1, CXCL2), epithelial neutrophil activating protein (CXCL5), interleukin-8 (CXCL8)." (PMID 40191727, 2025). "Intra-tumor injection of LL-37 significantly increased CXCL5, IL23A, MMP1a, and MMP9 mRNA expression in mouse B16F10 melanoma." (PMID 36980564, 2023). "In aggregate, our present study also suggested the pro-angiogenetic roles of TAMs through IL-23p19, CXCL5 and MMP-1 in melanoma." (PMID 36980564, 2023).
melanoma (continued). "LL-37 increased the mRNA expression and protein production of CXCL5, IL-23p19, and MMP-9 in A375 human melanoma cell lines." (PMID 36980564, 2023). "Intra-tumorally administered CRAMP, the mouse ortologe of LL-37, significantly increased the mRNA expression of CXCL5, IL23A, MMP1a, and MMP9 in B16F10 melanoma." (PMID 36980564, 2023). "In mouse melanoma and CRC, CAFs secrete CXCL5 to bind to c-x-c motif chemokine receptor 2(CXCR2) on cancer cells." (PMID 36759842, 2023). "Neutrophils of the tumour inflammatory infiltrate increase during melanoma progression, their accumulation depending on CXCL1, CXCL2, CXCL3, CXCL5, and CXCL8 molecules, which are stimulated by UV radiations." (PMID 35334544, 2022). "Experiments conducted on melanoma cell cultures have shown that CAFs release CXC motif chemokine 5 (CXCL5), which, in turn, induces PI3K/ protein kinase B (AKT)-dependent PDL-1 expression and resistance to immunotherapy in melanoma cells." (PMID 33036192, 2020). "The tumor stroma of melanoma had increased expression of POSTN upon administration with nivolumab, and POSTN stimulated TAMs to release CXCL5." (PMID 29643991, 2018). "The role of CXCL5 in recruiting CXCR2+ MDSC and TAN has also been shown in models of renal cell carcinoma (RCC), PDA, melanoma, and hepatocellular carcinoma (HCC)." (PMID 30319622, 2018). "Among these, CXCL1, CXCL2, and CXCL5 can bind to chemokine receptor CXCR2, which is expressed on several melanoma cell lines and mediates signaling to significantly facilitate their growth in vitro and in vivo." (PMID 29541408, 2018). "Correctively, LL-37-induced CXCL5, IL-23p19, MMP-1 and MMP-9 could promote angiogenetic activity in melanoma, leading to the local invasion of melanoma which contribute to T stage in melanoma patients." (PMID 36980564, 2023). "However, CXCL1, CXCL2, CXCL3, CXCL5 and CXCL8 mRNAs were significantly upregulated in melanoma samples compared to benign nevi." (PMID 37270599, 2023). "Aside from its direct effect on melanoma cells, CXCL8, along with other ligands of CXCR1 and CXCR2, namely CXCL1-3 and CXCL5-7, recruit innate cells, most notably neutrophils, which express the receptors CXCR1 and CXCR2 and are the “first responders” to tissue injury and damage." (PMID 34830780, 2021). "Baseline serum CXCL5, but not CXCL10 and CCL22, is associated with the efficacy of nivolumab in advanced melanoma." (PMID 32707850, 2020). "Baseline serum levels of CXCL5 were significantly increased in the response group compared to the non-response group in melanoma." (PMID 31080803, 2019). "Furthermore, exposure of melanoma cells to HFD serum induced the pro-inflammatory NF-κB pathway and also enhanced the expression of CXCL1, CXCL2 and CXCL5." (PMID 27049717, 2016). "Correctively, LL-37-induced CXCL5, IL-23p19, MMP-1 and MMP-9 could promote angiogenetic activity in melanoma tumor microenvironment, leading to the local invasion of melanoma which contributes to T stage in melanoma patients." (PMID 36980564, 2023). "Furthermore, in animal experiments with melanoma and CRC, the up-regulated expression of tumor PD-L1 induced by CAFs was reversed after silencing CXCL5’s receptor CXCR2.This suggests that the CXCL5-CXCR2 axis may be a promising therapeutic target." (PMID 36759842, 2023). "Indeed, peritumoral injection of CRAMP (the mouse ortologe of LL-37) increased the mRNA expression of CXCL5, IL23A, MMP1, and MMP9 in B16F10 melanoma in vivo, suggesting that LL-37 could enhance pro-angiogenesis in melanoma." (PMID 36980564, 2023). "In addition, other experimental studies revealed that adipocytes co-cultured with melanoma cells induce the secretion of chemoattractant factors (CXCL1, CXCL2, and CXCL5) added to a local immune cell recruitment, especially of M2 macrophages, in the “tumour niche”." (PMID 35334544, 2022).
melanoma (continued). "Notably, TAM-related chemokines, such as CXCL5, CXCL10, and CCL22, as well as a TAM-activation marker, soluble (s)CD163, could be predictive markers for efficacy and immune-related adverse events (irAEs) in anti-PD1 Abs-treated advanced melanoma patients." (PMID 34912726, 2021). "Since serum sCD163 and CXCL5 are, at least in part, derived from CD163+ TAMs that are activated by periostin, and chemokine profiles from TAMs are determined by the stimulation of stromal factors, spontaneously produced TAM-related factors could be detected in serum from melanoma patients." (PMID 31080803, 2019). "Unlike CXCL5, baseline serum concentrations of CXCL10 and CCL22 have not shown any correlations with the efficacy of nivolumab against advanced melanoma." (PMID 31417907, 2019).
hepatocellular carcinoma (40 papers, 2013 to 2026). A malignant tumor that arises from hepatocytes. "In hepatocellular carcinoma, increased CXCL5 level in the tumor microenvironment (TME) was associated with PD-L1+ neutrophile infiltration, which diminished T cell function." (PMID 37698493, 2023). "CXCL5 was also reported as a neutrophil attractant in hepatocellular carcinoma (HCC), associated with poor prognosis." (PMID 34503058, 2021). "Through systematic analysis, our results demonstrated that high CXCL5 expression was associated with reduced OS in intrahepatic cholangiocarcinoma (HR 1.91; 95% CI 1.31–2.78, p = 0.001) and hepatocellular carcinoma (HR 1.87; 95% CI 1.55–2.27, p < 0.001)." (PMID 29743818, 2018). "We found that high CXCL5 expression was associated with reduced OS in intrahepatic cholangiocarcinoma and hepatocellular carcinoma, which was consistent with previous studies." (PMID 29743818, 2018). "Furthermore, we found that high CXCL5 expression was associated with reduced OS in intrahepatic cholangiocarcinoma (HR 1.91; 95% CI 1.31–2.78) and hepatocellular carcinoma (HR 1.87; 95% CI 1.55–2.27)." (PMID 29743818, 2018). "High CXCL5 expression in hepatocellular carcinoma promotes tumor progression and mediates neutrophil infiltration." (PMID 38642131, 2024). "For example, CXCL5 chemokine, which was enriched in migrasomes, promotes proliferation, migration and invasion of hepatocellular carcinoma through activation of the PI3K and ERK1/2 signaling pathways as well as sequential infiltration of neutrophils." (PMID 37752917, 2023). "CXCL5 has been reported to recruit neutrophils in hepatocellular carcinoma to promote tumor growth and metastasis." (PMID 35027547, 2022). "CXCL5, also known as epithelial-derived neutrophil-activating peptide 78 (ENA-78), has been previously shown to induce TAN infiltration and increase metastatic risk in hepatocellular carcinoma." (PMID 34237033, 2021). "In hepatocellular carcinoma, CXCL5 was found to promote neutrophil infiltration and indicates poor prognosis." (PMID 33458757, 2021). "It has been reported that CXCL5 expression has been used as a prognosis predictor that is related to poor prognosis in many cancers, such as prostate cancer, endometrial cancer, hepatocellular carcinoma, and pancreatic cancer." (PMID 30792394, 2019). "The CXCR2/CXCL5 axis was also found to enhance epithelial-mesenchymal transition of hepatocellular carcinoma cells through the activation of the PI3K/AKT/GSK-3β/Snail signaling." (PMID 29743818, 2018). "Tumor-derived CXCL5 modulates the recruitment and activation of neutrophils, which in turn enhances the migration and invasion of human hepatocellular carcinoma (HCC) cells." (PMID 29556041, 2018). "The role of ENA-78/CXCL5 in appearance of TANs in carcinoma of the liver was investigated in 919 patients with hepatocellular carcinoma." (PMID 26819959, 2015). "Other studies have shown that CXCL5 is upregulated in various liver diseases and may play a role in hepatocellular carcinoma." (PMID 40643550, 2025). "In addition, RORα inhibited hepatocellular carcinoma proliferation, invasion and migration through downregulation of chemokine CXCL5." (PMID 38184549, 2024). "CXCR2/CXCL5 axis could activate PI3K/AKT signaling in hepatocellular carcinoma cells and also activate the STAT3 signaling pathway to promote the migration and invasion in gastric cancer." (PMID 33458757, 2021). "Hepatocellular carcinomas (HCC) have high expression of CXCL5, which attracts neutrophils, and is an indicator of poor prognosis." (PMID 33603130, 2022). "Mechanically, CXCL5 derived from hepatocellular carcinoma (HCC) cells is the strongest effector of neutrophil migration under hypoxic conditions." (PMID 33224886, 2020). "In hepatocellular carcinoma (HCC), tumor-derived chemokine CXCL5 mediate the recruitment of neutrophils, and the density of TANs is associated with poor prognosis of cancer patients." (PMID 27446967, 2016).
hepatocellular carcinoma (continued). "Additionally, SRY, via its downstream target SOX9, promotes hepatocellular carcinoma (HCC) progression by upregulating CXCL5 expression and activating the CXCL5/CXCR2 signaling axis, thereby enhancing tumor cell proliferation and invasion." (PMID 40438106, 2025). "It should be emphasised that, although CXCL5 and CXCR2 were mentioned, similar to anti-tumour chemokines, the CXCL5/CXCR2 axis, instead, can contribute to tumour invasion in hepatocellular carcinoma." (PMID 35406451, 2022). "Furthermore, IL-17 is reported to increase the tumor cell expression of CXCL5, thereby enhancing PMN-MDSC infiltration in hepatocellular carcinoma (HCC)." (PMID 37566060, 2023).
lung cancer (40 papers, 2013 to 2025). A malignant neoplasm involving the lung. "We found that high CXCL5 expression is associated with a poor prognosis and a decreased survival curve in lung cancer." (PMID 39034411, 2024). "CXCL5 overexpression in lung cancer is associated with poor differentiation, advanced disease stage, and poor overall survival, whereas CXCL5 deficiency is linked to reduced angiogenesis, delayed tumor progression, and metastatic tendencies." (PMID 36164329, 2022). "Clinical research has also found that a high CXCL5 expression level is associated with short overall survival and progression-free survival in lung cancer patients." (PMID 30718976, 2019). "It was reported that CXCL5 protein was higher in various lung cancer tissues, which was positively associated with tumor stage, lymph node metastasis, and worse survival." (PMID 29743818, 2018). "This study demonstrated that A2AR signaling mediated interaction between lung cancer cells and macrophages through NFκB, which regulated macrophage-derived CXCL5 expression." (PMID 38642131, 2024). "Our findings collectively demonstrate that CXCL5 promotes immune escape through PD-L1 upregulation in lung cancer and neutrophils chemotaxis through autocrine and paracrine mechanisms." (PMID 39034411, 2024). "We demonstrated that C-X-C motif chemokine ligand 5 (CXCL5) is markedly overexpressed in lung cancer cells and is positively correlated with a poor prognosis in patients with lung cancer." (PMID 39034411, 2024). "CXCL5-treated neutrophils further increased PD-L1 expression in lung cancer cells by releasing (granulocyte-macrophage colony-stimulating factor (GM-CSF)." (PMID 39034411, 2024). "In summary, our study revealed that CXCL5 overexpression can upregulate PD-L1 via PXN/AKT phosphorylation in lung cancer." (PMID 39034411, 2024). "To further investigate the biological functions of CXCL5 in lung cancer immunosurveillance, we established lung cell lines with either normal control(NC)or KD-CXCL5 using the Lipofectamine 3000 transient transfection method." (PMID 39034411, 2024). "In this study, we demonstrated the elevated expression of CXCL5 in lung cancer and explored its autocrine and paracrine roles." (PMID 39034411, 2024). "Immunofluorescence staining showed a significant decrease in PD-L1 expression in lung cancer cells when CXCL5 expression was knocked down." (PMID 39034411, 2024). "In a cohort comprising primary tumors from 208 patients with lung cancer, we measured the number of CD66b+ neutrophils and the expression of CXCL5, p-PXN, PD-L1, GM-CSF, CD8, PD-1, and T cell immunoglobulin-3 (TIM-3)." (PMID 39034411, 2024). "Conversely, patients with lung cancer exhibiting lower CXCL5 expression displayed less CD66b+ neutrophil infiltration, greater CD8+ T cell infiltration, and lower levels of p-PXN, PD-L1, GM-CSF, PD-1, and TIM-3 expressions." (PMID 39034411, 2024). "Our study revealed that lung cancer cells generate high levels of CXCL5, promoting cancer escape or suppressing antitumor immunity through either autocrine or paracrine mechanisms." (PMID 39034411, 2024). "We found that CXCL5 secretion was significantly increased in lung cancer cells, as evidenced by heatmap analysis." (PMID 39034411, 2024). "In this study, we observed marked overexpression of CXCL5 in lung cancer cells, which compromised CD8+ T cell-dependent antitumor immunity." (PMID 39034411, 2024). "Tumor-induced production of CXCL5 by SCs supported lung cancer spreading, epithelial-mesenchymal transition (EMT), and formation of metastasis in vivo, while SC-derived CCL2 promoted the M2 polarization of macrophages and lung cancer cell proliferation." (PMID 36551618, 2022).